RFX4 (regulatory factor X4)
Description:
Transcription factor that plays a role in early brain development. May activate transcription by interacting directly with the X-box. May activate transcription from CX3CL1 promoter through the X-box during brain development. May be required for neural tube ciliogenesis during embryogenesis (By similarity).
Synonyms: NYD-SP10
Tractability: No criterion of Open Targets' tractability assessment is met for any kind of drug.
Gene: Protein-coding gene on chromosome 12 (106,582,691 to 106,762,803, forward strand). Ensembl gene ENSG00000111783.
Subcellular location: Nucleus
Subcellular location (Human Protein Atlas): Nucleoplasm
Gene Ontology:
Molecular function: DNA-binding transcription activator activity, RNA polymerase II-specific; protein binding; RNA polymerase II cis-regulatory region sequence-specific DNA binding; sequence-specific double-stranded DNA binding; DNA-binding transcription factor activity, RNA polymerase II-specific; DNA binding; DNA-binding transcription factor activity
Biological process: positive regulation of transcription by RNA polymerase II; regulation of transcription by RNA polymerase II; regulation of DNA-templated transcription
Cellular component: chromatin; nucleus
Genetic constraint (gnomAD): Loss-of-function variants: 10 observed, 95.14 expected, observed/expected ratio (o/e) 0.11, 90% interval 0.064 to 0.18. The upper end of that interval is the gene's LOEUF score, 0.18, which puts it in group 1 of 6, group 1 being the genes least tolerant of losing a copy. Missense variants: 635 observed, 956.57 expected, observed/expected ratio (o/e) 0.66, 90% interval 0.62 to 0.71. Synonymous variants: 320 observed, 355.17 expected, observed/expected ratio (o/e) 0.9, 90% interval 0.82 to 0.99.
Homologues: Orthologues: chimpanzee RFX4 (99% identical), dog RFX4 (98% identical), pig RFX4 (98% identical), rabbit RFX4 (97% identical), mouse Rfx4 (97% identical), rat Rfx4 (96% identical), guinea pig RFX4 (94% identical), macaque RFX4 (88% identical), tropical clawed frog rfx4 (87% identical), zebrafish rfx4 (84% identical), Caenorhabditis elegans daf-19 (22% identical). Paralogues in human: RFX6 (38% identical), RFX3 (26% identical), RFX1 (25% identical), RFX2 (25% identical), RFX7 (18% identical), RFX8 (12% identical), RFX5 (9% identical).
Diseases named in the same sentence as RFX4 in open-access papers:
RFX4 is named in the same sentence as 29 diseases in open-access papers, as found by Europe PMC text mining. Sharing a sentence is not in itself a finding about the gene and the disease. The quoted sentences say what the papers report.
glioblastoma (4 papers, 2021 to 2023). The most malignant astrocytic tumor (WHO grade IV). "For example, RFX4 is a TF specifically expressed in the brain, and it has been recently revealed to be associated with tumor progression in patients with glioblastoma." (PMID 35227282, 2022). "Moreover, high expression of RFX4 is associated with tumor progression and poor prognosis in patients with glioblastoma." (PMID 36045400, 2022). "We identified a group of TF candidate genes with H4K5acK8ac-preferred promoters (e.g., ZNF883 and RFX4) and showed that they were also involved in the maintenance of glioblastoma stem-like properties." (PMID 37759202, 2023). "To investigate whether these genes with H4K5acK8ac-preferred promoters regulate glioblastoma stem-like properties, i. e., marker gene expression for stem cells and sphere formation efficiency, we disrupted ZNF883, RFX4, KLF11, and ZNF835 by siRNA knockdown in 0316-GSC cells." (PMID 37759202, 2023).
schizophrenia (3 papers, 2007 to 2024). A major psychotic disorder characterized by abnormalities in the perception or expression of reality. "Especially, Psychiatric and Chemo-dependency disorders were to be highly related to the RFX4 bound enhancers, which were composed of schizophrenia, tobacco use disorder." (PMID 38386071, 2024). "Also, according to our findings, RFX4 bound enhancer target genes were enriched in Neurological disease, Psychiatric disease, and schizophrenia terms." (PMID 38386071, 2024).
alcohol dependence (1 paper, 2024). Physical and psychological dependence on alcohol. "Also, recent GWAS study and cohort study indicate that the RFX family (including RFX4) genes are associated with autism, attention-deficit/hyperactivity disorder, and alcohol dependence." (PMID 38386071, 2024).
autoimmune disease (1 paper, 2015). A disorder resulting from loss of function or tissue destruction of an organ or multiple organs, arising from humoral or cellular immune responses of the individual to their own tissue constituents. "On the other hand, studies have shown that HLA-DRB1 has significant associations with autoimmune diseases and regulatory factor X 4 (RFX4)." (PMID 25836258, 2015). "Therefore, miR-499 may regulate HLA-DRB1 via the RFX4 pathway and participate in the pathogenesis of autoimmune diseases." (PMID 25836258, 2015).
bare lymphocyte syndrome (1 paper, 2008). "A fourth RFX gene (RFX4) was discovered in a human breast tumor tissue and the fifth, RFX5, was identified as a DNA-binding regulatory factor that is mutated in primary MHC class II deficiency (bare lymphocyte syndrome, BLS)." (PMID 18673564, 2008).
brain cancer (1 paper, 2022). A primary or metastatic malignant neoplasm affecting the brain. "In our analysis, RFX4 ranked first for the brain cancer class." (PMID 35227282, 2022).
ciliopathy (1 paper, 2018). A genetic disorder of the cellular cilia or the cilia anchoring structures, the basal bodies, or of ciliary function. "We have shown here that the mutant Rfx4 mice represent another ciliopathy disease model." (PMID 29298325, 2018).
congenital hydrocephalus (1 paper, 2018). Hydrocephalus that is present at birth. "Heterozygous deletion of Rfx4 resulted in severe, non-communicating congenital hydrocephalus associated with hypoplasia of the subcommissural organ." (PMID 29298325, 2018). "This phenotype resembled, but was less severe than, that of heterozygous mice in the Rfx4-insertional mutagenesis model, in which there was a 100% frequency of congenital hydrocephalus that was also characterized by enlarged olfactory ventricles, not seen in the current floxed KO model." (PMID 29298325, 2018). "We report here that heterozygous inactivation of Rfx4 led to apparent hypoplasia of the SCO, and that acetylated tubulin-labeled cilia were detached, both of which could lead to non-communicating congenital hydrocephalus." (PMID 29298325, 2018).
depression (1 paper, 2024). "Furthermore, previous GWAS systematically explored the genetic architecture in 2,965 complex traits and found that RFX4 may be associated with depression and chronotype." (PMID 38778419, 2024). "Multiple identified genes, such as RNASEL, RGS16, RFX4 and ROBO2 were reported to be associated with chronotype, depression or cognition in previous studies." (PMID 38778419, 2024). "We identified several candidate genes for sleep disorders in the subjects with depression, such as RFX4, RGS16 and ROBO2." (PMID 38778419, 2024). "Thus, RFX4, RGS16, RNASEL and ROBO2 may be the important genetic factors indirectly linked to sleep disturbances and depression via circadian rhythm or neurotransmitters." (PMID 38778419, 2024). "GWAS detected 15 loci significantly associated with chronotype in the subjects with self-reported depression, such as rs12736689 at RNASEL (P = 1.00 × 10− 09), rs509476 at RGS16 (P = 1.58 × 10− 09) and rs1006751 at RFX4 (P = 1.54 × 10− 08)." (PMID 38778419, 2024).
glioma (1 paper, 2014). A benign or malignant brain and spinal cord tumor that arises from glial cells (astrocytes, oligodendrocytes, ependymal cells). "RFX4 (regulatory factor X 4), a transcription factor known to influence HLA Class II expression is overexpressed in gliomas compared to normal brain tissues." (PMID 25026297, 2014).
holoprosencephaly (1 paper, 2018). Holoprosencephaly (HPE) is a complex brain malformation resulting from incomplete cleavage of the prosencephalon, occurring between the 18th and 28th day of gestation, and affecting both the forebrain and face, which results in neurological manifestations and facial anomalies of variable severity. "Homozygous inactivation of Rfx4 resulted in severe brain midline defects and failure of hemisphere formation, representing a form of holoprosencephaly, and demonstrated that RFX4 isoform 1 is crucial for early brain development." (PMID 29298325, 2018). "Homozygous deletion of Rfx4 resulted in formation of a single ventricle in the forebrain, and severe dorsoventral patterning defects in the telencephalon and midbrain at embryonic day 12.5, a collection of phenotypes that resembled human holoprosencephaly." (PMID 29298325, 2018).
Hydrocephalus (1 paper, 2018). Hydrocephalus is an active distension of the ventricular system of the brain resulting from inadequate passage of CSF from its point of production within the cerebral ventricles to its point of absorption into the systemic circulation. "Aberrations in Rfx3 and Rfx4 have been linked to hydrocephalus in mice." (PMID 29298325, 2018). "Since no excess CSF was present in the subarachnoid spaces of these Rfx4+/- mice, this represents a model of non-communicating hydrocephalus, as was true in the insertional mutation model." (PMID 29298325, 2018). "In the control mice, cilia were present in cells lining the lateral and third ventricles, but, in the Rfx4+/- mice with hydrocephalus, cilia were apparently detached in some areas from the cells lining the walls of the ventricles, or they were patchy or missing in some areas." (PMID 29298325, 2018). "Using an antibody specific to Reissner's fibers, we detected SCOs that were approximately 300 μm long on average (as seen in coronal serial sections) in the control mice, but they were only approximately 75 μm long on average in the Rfx4+/- mice with hydrocephalus (P< 0.01, n = 3)." (PMID 29298325, 2018). "Thus, the SCO was hypoplastic in the Rfx4+/- adult mice with hydrocephalus." (PMID 29298325, 2018).
Infertility (1 paper, 2019). "These genes play important roles in cell proliferation (RFX4, FOXM1, ASF1B), differentiation during spermatogenesis (CATSPERG, SPDYA, SPATA16, TSACC, TCP10L, DPY19L2) and motility of sperm cells during fertilization (DNAAF1); mutations in these genes may lead to infertility." (PMID 31671693, 2019).
narcolepsy (1 paper, 2021). A sleep disorder characterized by a tendency for excessive sleepiness during the day which occurs even after adequate sleep in the nighttime. "Overall, some autoreactive CD4+ T cells directed against RFX4 have been detected in narcolepsy patients, but also in healthy donors." (PMID 33837283, 2021). "Altogether, these findings reveal RFX4-specific CD4+ T cells in both post-Pandemrix and early-onset narcolepsy patients, therefore suggesting involvement of RFX4 in T cell immunity of theses narcoleptic cases and controls." (PMID 33837283, 2021). "One TCR (TCR165) from one patient but also another TCR (TCR173) from one healthy donor reactive against RFX4-86 used TRBV4-2, which has been strongly implicated in narcolepsy pathophysiology by our lab before through genetic analysis." (PMID 33837283, 2021). "Single cell TCR sequencing and phenotyping of more RFX4 specific CD4+ and CD8+ T cells could elucidate the role of RFX4 in the pathophysiology of narcolepsy." (PMID 33837283, 2021). "Importantly, the enrichment of TRBV4-2 in one narcolepsy patient and one healthy donor suggests the involvement of RFX4 CD4+ T cell autoreactivity in these donors." (PMID 33837283, 2021). "While the evidence we provide in this study suggests that autoantibodies against this peptide are rare and unlikely to be involved in the pathophysiology and onset of this condition, T cell reactivity against RFX4 peptides was sound in some narcolepsy patients, but also in healthy donors." (PMID 33837283, 2021). "Here we study whether autoimmunity directed against Regulatory Factor X4 (RFX4), a protein co-localized with hypocretin, is involved in some cases of narcolepsy." (PMID 33837283, 2021).
cancer (4 papers, 2015 to 2022). A tumor composed of atypical neoplastic, often pleomorphic cells that invade other tissues. "Among all the cancer types, RFX4 was exclusively expressed in GBM and LGG, and its expression in them was significantly higher than in the matched normal tissues." (PMID 35227282, 2022). "The transcription factor Rfx4, a highly upregulated transcript in TSP-1 deficient tumors, is believed to affect critical pathways in cancer such as WNT signaling." (PMID 26461935, 2015).
tumor (4 papers, 2012 to 2025). "RFX4 expression was found in normal healthy brain tissue and scattered in the tumor core in some patient cases." (PMID 40683881, 2025). "In the diffusely growing U3180MG xenografts, targeting of either HOPX or RFX4 prolonged survival, decreased tumor cell density, and (in the case of RFX4) led to altered morphology of the tumor cells." (PMID 40683881, 2025). "The RFX4-KO PDCX showed a marked reduction of tumor cells density." (PMID 40683881, 2025). "RFX4 expression was present in both normal brain tissue and the tumor core area." (PMID 40683881, 2025). "To understand the mechanisms underlying the altered growth and invasion phenotypes following KO interventions, we performed single-cell profiling of ANXA1-KO, RFX4-KO, and HOPX-KO tumor cells extracted from mouse brains." (PMID 40683881, 2025). "Before injecting the cells into mice, we conducted proliferation and self-renewal assays in vitro to ensure that ANXA1-KO, HOPX-KO, and RFX4-KO cells exhibited no discernible advantages in growth or tumor-forming capabilities." (PMID 40683881, 2025).
psychiatric disorder (2 papers, 2016 to 2024). A disorder characterized by behavioral and/or psychological abnormalities, often accompanied by physical symptoms. "It is noted that 7 genes, DAO, PRDX6, KCNN3, TCF7L2, RFX4, FYN, and B3GAT2 (yellow-colored nodes), relevant to psychiatric disorders are involved and interestingly these genes except B3GAT2 constitute a connected subgraph." (PMID 27510319, 2016).
infection (1 paper, 2024). The state of being infected such as from the introduction of a foreign agent such as serum, vaccine, antigenic substance or organism. "At 3 days post-infection (DPI 3), we confirmed the successful overexpression of RFX2, RFX3, RFX4, and RFX5 in stem cells." (PMID 38386071, 2024).
RFX4 also shares sentences with these, for which no sentence is quoted: Neurological disease (2 papers); attention deficit-hyperactivity disorder (1); autism (1); brain diseases (1); cardiac hypertrophy (1); dilated cardiomyopathy (1); lung carcinoma (1); mood disorder (1); sleep disorder (1); tobacco use disorder (1); type 1 narcolepsy (1).